INS (insulin)
Diseases named in the same sentence as INS in open-access papers (continued):
Sharing a sentence is not in itself a finding about the gene and the disease.
diabetes (continued). "Initial rhIGF-I application via BID (twice daily) injection was unsatisfactory, but continuous subcutaneous rhIGF-I infusion via an insulin pump improved weight development and diabetes control (HbA1c decreased from 10 to 7.6%)." (PMID 29695048, 2018). "Despite significant technological advances in insulin therapy over the last 20 years, hypoglycaemia continues to be a major barrier to the effective treatment of diabetes, which aims to prevent the development of diabetes-related complications." (PMID 28660491, 2018). "Now, almost hundred years after the discovery of insulin in 1921, the optimization problem of diabetes is well formulated as maintenance of strict glycemic control without increasing the risk for hypoglycemia." (PMID 32232090, 2018). "Diabetes-related cognitive impairment also results from disrupted insulin signaling and glucose homeostasis in the brain or diabetes-associated microvascular changes." (PMID 30065632, 2018). "Up to now, there is no large epidemiological study to investigate the relationship of insulin action to age, gender, BMI, WC, and WHtR in different glycemic statuses in Chinese population although the prevalence of diabetes increased sharply." (PMID 30211231, 2018). "The odds of developing IGT or diabetes increased to nearly fourfold when women needed insulin for the control of GDM during pregnancy and to nearly one-and-a-half-fold when they have positive family history of T2DM." (PMID 30186874, 2018). "Insulin-treated patients with type 1 (T1D, n = 122) and type 2 (T2D, n = 237) diabetes were identified through linkage with the Prescribed Drug Register and age-matched to 1771 women without diabetes." (PMID 30092829, 2018). "The resulting enhanced oxidative stress impairs the ability of the pancreas to secrete insulin, leading to the development of diabetes." (PMID 30361421, 2018). "In 1973, Roger Guillemin identified somatostatin, a pituitary polypeptide, capable of reducing the hyperglycaemia in insulin-free diabetes." (PMID 30405529, 2018). "Out of those who were on medication for diabetes, 237(57.5%) respondents were taking insulin alone; 128(31.1%) were taking oral hypoglycemic agents and the rest were on both insulin and oral hypoglycemic agents." (PMID 29505602, 2018). "Lower age (β = -0.18, p = 0.000), shorter diabetes duration (β = -0.10, p = 0.003), and using an insulin pump vs. multiple daily injections (β = 0.11, p = 0.000) were associated with better adherence." (PMID 30235290, 2018). "A group from Korea have evaluated a hypoglycaemia reduction course following structured intensive diabetes education for adults with type 2 diabetes treated with insulin or sulfonylureas." (PMID 28660491, 2018). "Milestones in the history of diabetes therapy include the discovery of insulin and successful methods of beta cell replacement including whole pancreas and islet cell transplantation options." (PMID 30057900, 2018). "Diabetes mellitus type 1 (DM1) and DM2 are by definition associated with recurrent hyperglycemia due to insufficient insulin production and insulin resistance, respectively." (PMID 30360467, 2018). "Sulfonylureas are prescribed typically for T2DM in patients with relative difficulty in glycemic control, such as those with a long duration of diabetes and low insulin levels." (PMID 29991356, 2018). "A third limitation relates to the possible misclassification of type of diabetes; specifically, the potential for people with insulin-treated type 2 diabetes to be labelled as having type 1 disease." (PMID 29075822, 2018). "Diabetes mellitus is characterized by hyperglycemia, a lackage of insulin action, insulin resistance, and the progression of diabetic pathology in the retina, renal glomerulus, and nerve." (PMID 29967293, 2018).
diabetes (continued). "On the contrary, in our view, it is vital to identify early predictors of insulin start: known duration of diabetes, low HDL-cholesterol, high HbA1c, BMI, triglycerides, and LDL-cholesterol values, as well as lipid-lowering treatment, eGFR, and retinopathy." (PMID 30327785, 2018). "In diabetes, insulin resistant visceral adipocytes augment influx of FFA in arterial endothelial cells that further activate metabolite sensitive pathways of vascular damage." (PMID 30170601, 2018). "T2DM constitutes up to 90% of all diabetes and it is characterized by chronic hyperglycaemia resulting from defects in insulin secretion and/or insulin action and metabolic disorders of protein and lipids." (PMID 29785210, 2018). "After the ITQ was published, the Brazilian Diabetes Society proposed a new guideline about insulin injections, and the information is being spread by many kinds of media." (PMID 30498521, 2018). "Currently, exogenous insulin therapy is still considered to be the gold standard when managing diabetes, though stem cell biology is recognized as one of the most promising strategies for restoring endocrine pancreatic function." (PMID 30233489, 2018). "Clinically, the inhibition of hepatic insulin clearance seems likely to be a therapeutic target for diabetes." (PMID 29415457, 2018). "For millions of people worldwide living with diabetes mellitus (422 million in 2014, World Health Organization, 2016]), an oral dosage form of insulin would significantly increase the quality of life." (PMID 30394120, 2018). "Due to the inadequate produced insulin, type 1 Diabetes mellitus patients need life-long insulin therapy and tight glucose monitoring." (PMID 30413974, 2018). "Insulin (and the Insulin Growth Factor axes) appears to be an important factor linking diabetes and breast cancer." (PMID 29486734, 2018). "Strenuous exercise itself has a favorable effect in controlling diabetes through increasing glucose utilization in muscle and insulin sensitivity." (PMID 29672520, 2018). "In all models, FPG was most strongly associated with incident diabetes, followed by 2hPG, HbA1c, HOMA-IR and fasting insulin." (PMID 29018885, 2018). "For diabetes study, both random forest and GBM have identified magnesium, chloride, c-peptide of insulin, insulin, and uric acid as important variables for predicting diabetes." (PMID 29650030, 2018). "Diabetes mellitus is a chronic metabolic disease of hyperglycemia resulting from defects in insulin secretion, action, or both." (PMID 29503662, 2018). "Diabetes mellitus (DM) is a pandemic metabolic problem characterized by hyperglycemia due to defects in secretion or action of insulin, namely, type 1 or type 2 diabetes mellitus (T2DM), respectively." (PMID 30116165, 2018). "The presence of diabetes and in particular insulin-treated diabetes is an independent and strong predictor of late and repeat coronary revascularization, in all patients undergoing baseline coronary angiography with or without revascularization." (PMID 29402330, 2018). "A number of studies have shown that individuals with insulin-dependent and non-insulin-dependent diabetes mellitus have improved sensitivity to insulin and improved glycemic control after exercise training." (PMID 30324108, 2018). "The association of PA with improved insulin sensitivity and reduced utilization of diabetes medications has been well documented, which may have explained, in part, the reductions in use of diabetes medications that were reported by some individuals in this study." (PMID 29668741, 2018). "Escherichia coli can produce a material very similar to insulin, which was found to block insulin by binding to the target cell of insulin and leads to diabetes." (PMID 30544624, 2018). "In patients who had undergone bariatric surgery, about 8% showed complete remission of diabetes while more than 90% showed a significant decrease in their insulin or OADs requirement." (PMID 29527102, 2018).
diabetes (continued). "Several miRNAs were identified to play a role in diabetes by regulating insulin signaling and glucose metabolism." (PMID 30013975, 2018). "The etiology of diabetes is twofold and involves reduced insulin secretion and increased insulin resistance." (PMID 30151373, 2018). "Disruption of the circadian timing system resulted in a significant decrease in glucose-stimulated insulin secretion, while disruption of the core clock components Clock and Bmal1 led to hypoinsulinemia and diabetes." (PMID 29385702, 2018). "Potential confounding by indication was addressed in case-only analyses and additional analyses comparing insulin-treated diabetes patients with patients receiving other glucose-lowering medication." (PMID 30092829, 2018). "This was coupled with the presence of soluble dietary fiber, arabinose, and fructose in both the sample and its compounded diet which delaying gastric emptying, inhibiting glucagon secretion, and stimulating insulin secretion in diabetic mellitus animals." (PMID 29387371, 2018). "Availability of the basic drugs for treatment of diabetes such as metformin, sulfonylureas, and insulin is reportedly low, while treatment monitoring is sub-optimal given the low access to fasting glucose testing and glycated hemoglobin (HbA1C) testing." (PMID 30591044, 2018). "Type 1 diabetes mellitus (T1D) is characterized by T-cell-mediated autoimmune destruction of insulin secreting pancreatic beta cells." (PMID 30412637, 2018). "The central roles of the pancreas and insulin producing islets of Langerhans in the development of diabetes were established in the late nineteenth century." (PMID 30057900, 2018). "Diabetes mellitus is a group of metabolic disorders characterized by elevated blood sugar and abnormalities in insulin secretion and action." (PMID 29755566, 2018). "One possible explanation is that combining tramadol with metformin increased hepatic insulin sensitivity, resulting in hypoglycemia in diabetes." (PMID 30355965, 2018). "Observational studies generally observe that higher fiber containing fruits are associated with lower diabetes risk and better control of diabetes risk biomarkers such as HOMA-IR, HbA1c and fasting insulin, and lower risk of diabetic retinopathy." (PMID 30487459, 2018). "The Group 2 (whose clinical inertia during the first 2 years after insulin therapy introduction was also studied) had 56% females, age of 67.1 ± 10 years and clinical diabetes duration of 17.3 ± 6.3 years." (PMID 30386438, 2018). "We should note that the uptake of granules correlated with the transfer of immunogenic insulin in the case of the diabetes-prone islets of the NOD mouse." (PMID 29589072, 2018). "We describe the frequency of hypoglycemia recurrence requiring further emergency department evaluation who have been recently discharged from the emergency department and are taking oral diabetes medications or long-acting insulin." (PMID 29799604, 2018). "These collective results suggest that increased cholinergic signaling is a compensatory neural mechanism to increase insulin secretion in pre-diabetes and type 2 diabetes develops if this adaptation fails." (PMID 29466430, 2018). "Indigenous Australians were younger at entry (median age 63.3 [54.7–67.8] vs 69.6 [63.3–75.4]), more commonly current smokers (56.3% vs 31.4%), and more frequently had insulin-treated diabetes (18.8% vs 5.2%)." (PMID 29769031, 2018). "Thus, early diagnosis and adequate treatment of an underlying psychiatric disorder in obese children are very important for the improvement of impaired insulin sensitivity and may serve to decrease the risk of developing diabetes, hypertension and cardio-vascular disease in these subjects." (PMID 29789273, 2018). "Diabetes was defined as fasting plasma glucose of 7.0 mmol/L or higher, a history of diabetes, or the use of insulin or oral antidiabetic drugs." (PMID 29671082, 2018).
diabetes (continued). "The presence of diabetes resulted in a significantly higher insulin concentration after 360 min (P = 0.048)." (PMID 29370144, 2018). "For this reason, disease coding has been combined with other information (e.g., current prescriptions for insulin or oral hypoglycemic medication) when estimating diabetes type in these data." (PMID 29596402, 2018). "In this study, subjects with a nonpositive insulinogenic index were characterized based on insulin secretion and insulin sensitivity and diabetes and IGT incidences were compared with subjects who had a positive insulinogenic index." (PMID 29765987, 2018). "Such subacute depletion of PHD3 in vivo improved insulin sensitivity and glucose tolerance, and thereby ameliorated diabetes." (PMID 30250231, 2018). "Literature on the treatment of diabetes in hospital even encouraged patients to self-manage their insulin when hospitalized on the condition that this is also monitored by healthcare providers." (PMID 30049965, 2018). "With regard to the mechanisms of insulin-induced diabetes remission, the focus appears to be on the ability of insulin to improve insulin secretion, although in post-bariatric patients insulin resistance also abates as a result of the large weight loss." (PMID 30142908, 2018). "Before the discovery of insulin as well as common anti-diabetes drugs, patients with diabetes were treated with medicinal herbs and traditional treatments." (PMID 30474605, 2018). "After adjusted for the duration of diabetes, BMI, and postprandial C peptide, insulin treatment was a significant predictor for IAA positivity (OR = 5.20, p < 0.0001)." (PMID 29887833, 2018). "Patients with LDLc ≤ 2.5 mmol/l had a longer diabetes duration (P = 0.006) and more often used insulin (P = 0.02)." (PMID 29695715, 2018). "Both, at diabetes onset and at follow-up, endogenous insulin release is higher in CHI patients with diabetes than in patients with T1DM, apparently due to the remaining beta cell mass." (PMID 30577875, 2018). "It is worth noting that glucose homeostasis is tight regulated by the reciprocal control exerted by insulin and glucagon circulating levels, and that hyperglucagonemia is recognized to account for hyperglycemia and diabetes development." (PMID 30532260, 2018). "Both diabetic models produced hyperglycemia, polyphagia, polydipsia, insulin resistance, high fructosamine, hepatic damage and reduced insulin, although only DE presented human diabetes-like alterations, such as dyslipidemia and neuropathy symptoms." (PMID 29924854, 2018). "Once diagnosed, pre-diabetes management relies on the combination of diet modification and administration of insulin sensitizers such as metformin." (PMID 29596390, 2018). "Those who enrolled via the indirect channel included more male and were younger and less often to use insulin and to have family members with diabetes than those via the direct channel." (PMID 29988655, 2018). "T1DM is an autoimmune insulin-dependent disease characterized by remarkable reduction in insulin production and chronic hyperglycemia, and accounts for approximately 10% of all diabetes cases." (PMID 29451877, 2018). "For example, it has been reported that impairment of circadian rhythms leads to the development of diabetes via the induction of abnormal insulin secretion, decreased sensitivity to insulin, and exacerbated inflammation." (PMID 30344606, 2018). "Impaired response to insulin action in fat, muscle and liver cells induces a breakdown of fat, a failure of glycogenesis, and excess insulin secretion at early stages of diabetes." (PMID 29587416, 2018). "Loss of function mutations in HNF1A cause the most common form of monogenic diabetes (HNF-1A-MODY;MODY3), a disorder characterized by reduced glucose-stimulated insulin secretion." (PMID 30143652, 2018).
diabetes (continued). "Supportive behaviors included the provision ofemotional support, such as empathy and alleviation of diabetes-related distress, andthe provision of instrumental support such as paying for medications and helpingparticipants apply insulin." (PMID 30066604, 2018). "Combining the GLP-1 agonist liraglutide and insulin did not appear to provide any additional effect compared to liraglutide or insulin alone in type 2 diabetes mellitus." (PMID 30384842, 2018). "Sensory neuropathy occurrence has been related with insulin resistance and appears at early stages of diabetes, even before changes on insulin or glucose plasma levels can be noticed." (PMID 30322196, 2018). "Patients with diabetes on insulin therapy use sharps (e.g., needles) on a regular basis and a considerable proportion of them, within their home environments." (PMID 30555274, 2018). "Mutations in KCNJ11 lead to a permanent opening of the potassium channel in the pancreatic b cells, thus preventing any activation of voltage-dependent calcium channel and glucose-induced insulin secretion leading to diabetes." (PMID 28766502, 2018). "Smad7 also participates in beta cell function and insulin secretion, since overexpression of Smad7 in beta cells results in reversible diabetes in mice." (PMID 30322036, 2018). "There was a wide range of educational attainment, the mean duration of diabetes was 11 years, 36% of participants self-reported a diabetes-related health complication, and 40% reported current treatment with insulin." (PMID 30400859, 2018). "Use of SMBG is a fundamental component of self-management for individuals with diabetes, particularly those treated with insulin or other insulinotropic medications." (PMID 28946757, 2018). "Patients were admitted to drugs such as Nifedipine, Methyldopa, Losartan and Lisinopril for hypertension; and Metformin and Insulin for diabetes." (PMID 29590156, 2018). "Insulin has been used to treat diabetes for almost 100 years, whereas the primary clinical use of glucagon is limited to the acute treatment of insulin-induced hypoglycemia." (PMID 29558502, 2018). "We also investigated further possible pathogenetic factors of GV including HbA1c, body mass index (BMI), gender, age, daily insulin dose, diabetes duration, and frequency of hypoglycemia." (PMID 29725320, 2018). "Type 1 and 2 diabetes are both caused by immune-mediated destruction and dysfunction of pancreatic beta cells, eventually causing defective glucose-stimulated insulin secretion (GSIS) and beta cell apoptosis in diabetes." (PMID 29769837, 2018). "PPARγ is a target of synthetic insulin sensitizers thiazolidinediones (TZDs), including pioglitazone and rosiglitazone, which were used in the treatment of type 2 diabetes mellitus (T2DM)." (PMID 30060458, 2018). "Skeletal muscle is the primary site of insulin-mediated glucose uptake and is the main organ affected by insulin resistance and diabetes." (PMID 29921793, 2018). "In this survey of a general population of patients with type 2 diabetes, the mean diabetes duration was 8.4 years, and 31% of patients were treated with insulin, either on its own or in combination with oral agents." (PMID 30486889, 2018). "In humans, carriers of a frameshift deletion of exon 9 in the LIPE gene, encoding for HSL, were characterized by metabolic dysfunction, including dyslipidemia, hepatic steatosis, systemic insulin resistance, and diabetes." (PMID 30086728, 2018). "In an early double-blind cross-over study of 11 patients with non-insulin treated diabetes, Aro and colleagues observed reduction in fasting and post-prandial glucose following 3 months of dietary supplementation with 21 g of guar gum per day in divided doses." (PMID 30170579, 2018). "Open dialogue with the patient throughout the continuum of diabetes management, with an emphasis on the positive benefits of insulin therapy, will significantly enhance the outcomes for patients with diabetes." (PMID 29476414, 2018).